C1GALT1 (core 1 synthase, glycoprotein-N-acetylgalactosamine 3-beta-galactosyltransferase 1)
Diseases named in the same sentence as C1GALT1 in open-access papers (continued):
Sharing a sentence is not in itself a finding about the gene and the disease.
colitis (9 papers, 2014 to 2025). Inflammation of the colon. "Deficiency of C1galt1, critical for core 1 O-glycosylation of mucin, results in the failure of normal mucus layer formation and spontaneous development of colitis, similar to MUC2-deficient mice." (PMID 39589551, 2024). "C1GALT1, expressed throughout the colon, controls the synthesis of core 1 O-glycans and its knockout in mice causes spontaneous colitis in the distal regions of the colon." (PMID 37070602, 2023). "It has been shown in the literature that mice with C1GalT1 and C3GnT knockout have increased susceptibility to colitis, MUC2 level also was decreased, the total glycan chains were shorter, and the microflora was changed." (PMID 31731602, 2019). "Several genetic mouse models with profound mucus layer permeability, such as MUC2, NHE3, and C1GALT1 knock‐out mice, developed colitis." (PMID 37691494, 2023). "Prior studies showed that mice that lack intestinal C1galt1–/– are unable to galactosylate GalNAc or mucin O-glycans, leading to an attenuation of the O-glycan structure in the mucus layer, resulting in spontaneous colitis." (PMID 40153534, 2025). "EPR cKO mice, whose phenotype is more evident in the proximal colon where B3GNT6 is predominantly expressed, display normal levels of C1GALT1 and, as in B3GNT6 knockout, colitis is only apparent upon DSS challenge." (PMID 37070602, 2023).
pancreatic cancer (8 papers, 2021 to 2025). "Another study showed loss of C1GALT1 in pancreatic cancer is correlated with poor prognosis and metastasis." (PMID 35169131, 2022). "Pancreatic cancer also revealed substantial differences (p = 0.01981), with normal tissues having a lower median of C1GALT1 gene expression than tumor tissues." (PMID 40548474, 2025). "Our data showed that itraconazole treatment decreased C1GALT1 levels and increased Tn antigens on cell surfaces in HPAC cells, confirming that itraconazole is also a C1GALT1 inhibitor in pancreatic cancer cells." (PMID 33420364, 2021). "Using data from the Oncomine database, C1GALT1 mRNA levels are found to be significantly increased in pancreatic cancer compared with normal pancreatic tissues in both the Pei and Badea Pancreas datasets." (PMID 33420364, 2021). "Patients of pancreatic cancer with high C1GalT1 expression were shown to survive 18 months less compared to those with low C1GalT1 expression within 4 years." (PMID 34944925, 2021). "Together, these results suggest that loss of C1galt1 led to the more aggressive phenotype than the one in KPC mice and that the MUC16 protein plays a role in pancreatic cancer." (PMID 34368082, 2021). "However, human pancreatic cancer cells with knockout of C1GALT1 had an increased tendency for tumorigenesis and metastasis." (PMID 35936713, 2022). "Overexpression of C1GalT in pancreatic cancer reduced the appearance of the TF precursor structure Tn on integrin-αV and -α5 whereas knockdown of C1GalT1 in T3M4 PDAC cells increased Tn occurrence on mucin protein MUC16 and increased phosphorylation of integrin-α4." (PMID 34944925, 2021). "Overexpression of C1GALT1, a key enzyme controlling the elongation of the Tn-antigen to T-antigen in turn was also found to enhance migration, invasion, tumour growth, and metastasis of pancreatic cancer cells." (PMID 34279699, 2021). "Therefore, we proposed that the integrin-mediated pathway is coordinated with other C1GALT1-regulated pathways, including RTKs and mucins, to promote tumor growth and metastasis in pancreatic cancer." (PMID 33420364, 2021). "Also in pancreatic cancer, C1GALT1 knockdown significantly inhibited cell adhesion to the extracellular matrix (ECM), which was associated with a decrease in FAK phosphorylation at Y397/Y925 as well as changes in O-glycans on integrins (including β1, αv and α5 subunits)." (PMID 38699634, 2024). "In a study of pancreatic cancer, by using the CRISPR/Cas9 system to disrupt C1GALT1 in human pancreatic ductal adenocarcinomas cells, the results showed enhanced invasiveness and metastatic ability of these cells and increased production of Tn." (PMID 38699634, 2024). "C1GalT1-mediated truncation of O-glycans on CD44 inactivates the ERK/NF-κB signaling pathway, resulting in NANOG expression in pancreatic cancer (PC) cells and changes in tumor stem cell characteristics." (PMID 35936713, 2022).
bladder cancer (7 papers, 2022 to 2025). "Consistent with the Xena results, tumor tissues of the stomach, pancreas, lung, and bladder cancers showed significantly higher C1GALT1 expression compared to normal tissues." (PMID 40548474, 2025). "Analysis of bladder cancer cell lines (5637, KK47, J82, T24, and YTS-1) and normal bladder epithelial cells (HUC-1 and HCV29) revealed greater expression of C1GALT1 in bladder cancer cells than in normal cells." (PMID 39126245, 2024). "This regulatory process inhibits the pro-tumorigenic effect of C1GalT1 on bladder cancer and establishes a beneficial feedback loop." (PMID 39126245, 2024). "Our study demonstrated that C1GalT1 expression is markedly increased in invasive bladder cancer cells compared to noninvasive bladder cancer cells and normal bladder cells." (PMID 39126245, 2024). "The TCGA database also showed enhanced C1GalT1 expression in bladder cancer tissues compared to normal tissues." (PMID 39126245, 2024). "The T antigen is a glycan epitope produced by C1GalT1 that is highly prevalent in bladder cancer cells but rarely expressed in normal bladder cells." (PMID 39126245, 2024). "To date, few studies have addressed the role of C1GALT1 in bladder cancer (BLCA), and molecular mechanisms that underlie C1GALT1 dysregulation are unclear." (PMID 35864552, 2022). "Abnormal expression of C1GALT1 and its products T antigen in human bladder cancer (BLCA) were evaluated with BLCA tissue, plasma samples and cell lines." (PMID 35864552, 2022). "Furthermore, a decrease in C1GalT1 inhibits the pro-tumorigenic effect on bladder cancer cells by suppressing glycolysis." (PMID 39126245, 2024). "Glycosyltransferase, C1GALT1, is controlled in bladder cancer (BLCA) by the cHP1BP3 (circRNA produced from HP1BP3) –miR-1-3p axis, which represses and decreases the migratory ability and proliferation of BLCA cells in vitro and in vivo by altering target glycoproteins." (PMID 38191389, 2024). "In addition, C1GALT1 affects the migratory ability, proliferation and colony formation of bladder cancer cells through a mechanism of miR-1-3p/cHP1BP3 axis deregulation and shows tumor suppressor activity in bladder cancer cells." (PMID 38699634, 2024). "C1GALT1 levels were consistent with FGFR3 expression levels, a specific bladder protein, in bladder cancer." (PMID 38845937, 2024).
head and neck cancer (7 papers, 2018 to 2025). A primary or metastatic malignant neoplasm affecting the head and neck. "In this study, we showed that the loss of core‐1 β1,3‐galactosyltransferase (C1GALT1)‐mediated O‐glycosylation suppressed tumor growth in syngeneic head and neck cancer mouse models." (PMID 37452653, 2024). "Lin explained that the loss of C1GALT1 inhibited tumor growth in the mouse models of head and neck cancer." (PMID 38845937, 2024). "Except for prostate and head and neck cancers, some genes were positively correlated, and some genes were negatively correlated with C1GALT1 in metastasis." (PMID 40548474, 2025). "In addition, in head and neck cancer, the C1GALT1 gene expression was mostly negatively correlated with over‐expressed genes in metastasis and positively correlated with under‐expressed genes in metastasis." (PMID 40548474, 2025). "Itraconazole has been reported to degrade and inhibit C1GALT1 protein in head and neck cancer, suggesting that this drug could mimic the antiproliferative effect of C1GALT1 knockdown and thus potentially serve as a prototype therapeutic agent for osteosarcoma." (PMID 38622340, 2024). "O-glycosylation of EGFR was blocked by C1GALT1 knockdown in head and neck cancer." (PMID 34452648, 2021). "MCM6 showed similar correlations, except in HPV+ head and neck cancer, while MCM4 was positively correlated with C1GALT1 across all cancer types." (PMID 40548474, 2025).
head and neck squamous cell carcinoma (5 papers, 2021 to 2025). A squamous cell carcinoma that arises from any of the following anatomic sites: lip and oral cavity, nasal cavity, paranasal sinuses, pharynx, larynx, and salivary glands. "In head and neck squamous cell carcinoma, overexpression of C1GalT1 has been linked to poor prognosis and increased cell invasiveness." (PMID 40548474, 2025). "In head and neck squamous cell carcinoma (HNSCC), suppressing C1GalT1 expression by siRNA shortened the EGFR O-linked sugar chains and decreased the affinity of EGF binding to EGFR." (PMID 34944925, 2021).
IgA nephropathy (5 papers, 2009 to 2024). "The enzyme has also been linked to IgA nephropathy by deposition of galactose-deficient IgA1 (Gd-IgA1) circulating in the patients with C1GALT1 mutation." (PMID 35784319, 2022). "Coincident associations at the loci encompassing the C1GALT1 and ST6GAL1 genes contribute to a better understanding of the factors involved in IgA nephropathy (IgAN) risk." (PMID 39123268, 2024). "In IgA nephropathy, miR-148b, which potentially targets core 1 synthase, glycoprotein-N-acetylgalactosamine 3-beta-galactosyltransferase 1 (C1GALT1), was upregulated." (PMID 23683438, 2013).
neuroblastoma (5 papers, 2022 to 2025). Neuroblastoma (NB) is the most common solid, extracranial childhood tumor. "In pancreatic ductal adenocarcinoma (PDAC), neuroblastoma, and endometrial cancer, reduced C1GALT1 expression was associated with more aggressive phenotype of tumor." (PMID 38662050, 2024). "In addition, reduced C1GALT1 expression was associated with improved survival of neuroblastoma patients." (PMID 38662050, 2024). "In PDAC, neuroblastoma, as well as endometrial cancer, the expression of C1GALT1 was significantly decreased in poorly differentiated samples compared to well-differentiated samples." (PMID 38662050, 2024). "However, in neuroblastoma, higher C1GALT1 expression correlates with better outcomes, highlighting the need to further investigate its role in OS." (PMID 39844613, 2025). "In contrast, no apparent inhibition was observed following C1GALT1 knockdown in IMR-32 neuroblastoma cells, a cell line with less intense C1GALT1 expression." (PMID 38622340, 2024).
osteosarcoma (5 papers, 2024 to 2025). A usually aggressive malignant bone-forming mesenchymal neoplasm, predominantly affecting adolescents and young adults. "To validate this association between C1GALT1 expression and osteosarcoma cell proliferation in vivo, we selected G292 as the cell with the most stable tumor engraftment in subcutaneous injection into mice and confirmed that knockdown of C1GALT1 by siRNA reduced the growth of G292." (PMID 38622340, 2024). "C1GALT1 expression and clinicopathological and biological characteristics of osteosarcoma (OS) patients." (PMID 39844613, 2025). "This study investigates the role of core 1 β1,3‐galactosyltransferase 1 (C1GALT1) in osteosarcoma, focusing on its implications in chemoresistance." (PMID 39844613, 2025). "C1GALT1 enhances the drug resistance and metastatic propensity of osteosarcoma by promoting lysosomal degradation and effluence." (PMID 40646517, 2025). "Elevated levels of C1GALT1 were observed in doxorubicin‐selected osteosarcoma cells, where its suppression significantly promoted doxorubicin‐induced apoptosis and reduced drug efflux." (PMID 39844613, 2025). "This strategy identified the galactosyltransferase Core 1 synthase glycoprotein-N-acetylgalactosamine 3-beta-galactosyltransferase 1 (C1GALT1) as a promising biomarker of poor prognosis and a feasible treatment target for osteosarcoma." (PMID 38622340, 2024). "Among the genes upregulated in the poor survival group, siRNA-mediated knockdown of the glycosylation-related gene C1GALT1 suppressed osteosarcoma cell proliferation in culture." (PMID 38622340, 2024). "To further assess the functions of C1GALT1 in osteosarcoma cells, we examined changes in the gene expression profiles of cell lines following C1GALT1 knockdown or itraconazole treatment by RNA sequencing." (PMID 38622340, 2024). "It has been reported that the azole antifungal drug itraconazole inhibits the polymerization and function of C1GALT1 protein in some carcinomas, so we examined its effects on C1GALT1 expression in osteosarcoma cells." (PMID 38622340, 2024). "Functional analyses of differentially expressed genes between cases with poor and better prognosis identified C1GALT1 as a promoter of osteosarcoma cell proliferation and thus as a potentially useful prognostic marker and therapeutic target." (PMID 38622340, 2024). "Up-regulation of C1GALT1 promotes the proliferation of osteosarcoma cells in vitro but exhibits a significant growth inhibitory effect after 3 weeks post-implantation in xenograft models in vivo." (PMID 38534381, 2024). "Interestingly, a very recent study found that in osteosarcoma, C1GALT1 is highly expressed and promotes cell proliferation and tumor growth by maintaining ERK signaling." (PMID 39894896, 2025). "Moreover, the C1GALT1 inhibitor itraconazole suppressed osteosarcoma cell proliferation in culture, while doxycycline-induced shRNA-mediated knockdown reduced xenograft osteosarcoma growth in mice." (PMID 38622340, 2024). "Elevated C1GALT1 expression is a potential early predictor of poor prognosis, while pharmacological inhibition may be a feasible treatment strategy for osteosarcoma." (PMID 38622340, 2024). "Further studies on C1GALT1 activity in osteosarcoma are necessary to clarify its role." (PMID 38534381, 2024). "Furthermore, among the genes differentially expressed between these clinical groups, C1GALT1 was upregulated in the poor prognosis group, and C1GALT1 knockdown reduced the osteosarcoma cell proliferation rate in culture and tumor model mice." (PMID 38622340, 2024). "The effects of C1GALT1 on signaling protein phosphorylation have been reported to vary depending on the malignancy, so we also examined the relationships between C1GALT1 expression and protein phosphorylation in osteosarcoma using protein arrays." (PMID 38622340, 2024). "In vitro and in vivo studies confirmed that C1GALT1 impacts ABCC1 expression and function, further supporting its role in osteosarcoma chemoresistance." (PMID 39844613, 2025).
osteosarcoma (continued). "Therefore, combined C1GALT1 and MMP3 inhibition could be an even more effective candidate therapy for osteosarcoma." (PMID 38622340, 2024).
pancreatic ductal adenocarcinoma (5 papers, 2020 to 2025). An infiltrating adenocarcinoma that arises from the epithelial cells of the pancreas. "The deletion of C1GALT1 caused an aggressive phenotype in the context of pancreatic ductal adenocarcinoma." (PMID 32075174, 2020). "We recently published a role of C1GALT1 in pancreatic ductal carcinoma using in vitro and in vivo KO models." (PMID 32075174, 2020). "Additionally, another study demonstrated that C1GALT1 was overexpressed in 85% of pancreatic ductal adenocarcinoma tumors compared to adjacent non‐tumor tissues and was associated with poor survival outcomes in these patients." (PMID 40548474, 2025). "Likewise, pancreas-specific C1GALT1 disruption originated O-glycosylation truncation that promoted early metastasis and stimulated a more aggressive pancreatic ductal adenocarcinoma phenotype." (PMID 36745330, 2023).
endometrial cancer (4 papers, 2023 to 2025). Primary or metastatic malignant neoplasm involving the endometrium (mucous membrane that lines the endometrial cavity). "More importantly, we also here demonstrate that the increase on proliferation, invasion and migration of ECC-1 endometrial cancer cells upon depletion of C1GALT1 was associated to the overexpression of ANXA1." (PMID 36745330, 2023). "Higher C1GALT1 expression was also seen in bladder, lung, and endometrial cancer types, which were similar to those in our study." (PMID 40548474, 2025). "Depletion of C1GALT1 also induced the expression of invasive proteins in endometrial cancer, increasing the invasion ability of cancer cells." (PMID 38845937, 2024). "Here, we focused the study on the analysis of the implication of low expression of C1GALT1 observed in this report in endometrial cancer, which account for 75–80% of all uterine cancers." (PMID 36745330, 2023). "Therefore, although other players would also be responsible of these effects, we were able to demonstrate the causal correlation between C1GALT1 and ANXA1 protein expression with tumorigenic and metastatic properties of endometrial cancer cells." (PMID 36745330, 2023). "Therefore, we hypothesized that the upregulation of ANXA1 upon C1GALT1 depletion could be associated to the increase in proliferation, invasion and migration of ECC-1 endometrial cancer cells." (PMID 36745330, 2023). "Collectively, these results correlate C1GALT1 and ANXA1 protein expression with tumorigenic and metastatic properties of endometrial cancer ECC-1 cells." (PMID 36745330, 2023).
esophageal cancer (4 papers, 2020 to 2024). A primary or metastatic malignant neoplasm involving the esophagus. "They discovered that the loss of C1GALT1 resulted in increased radiosensitivity of esophageal cancer cells." (PMID 32075174, 2020). "Previous mechanistic investigations in esophageal cancer and laryngeal cancer highlighted the role of C1GALT1-mediated O-glycosylation of β1-integrin in regulating radiosensitivity." (PMID 38662050, 2024). "Recent studies indicated that C1GALT1 functions as a regulator of radiosensitivity in human esophageal cancer and laryngeal cancer." (PMID 38662050, 2024). "C1GALT1 knockdown enhanced radiosensitivity of esophageal cancer cells, and suppressed irradiation-enhanced migration and invasion by modifying glycosylation of integrin β1." (PMID 35864552, 2022). "Furthermore, two reports showed that C1GALT1 could induce radioresistance in human esophageal cancer and laryngeal cancer cells through the modification of β1-integrin glycosylation." (PMID 38662050, 2024). "It has been found in the study of esophageal cancer, another epithelial cell carcinoma that the expression level of C1GALT1 was positively correlated with MUC1 O- glycosylation, and the co expression of MUC1 and C1GALT1 was negatively correlated with survival rate." (PMID 38699634, 2024).
lung adenocarcinoma (4 papers, 2021 to 2025). A carcinoma that arises from the lung and is characterized by the presence of malignant glandular epithelial cells. "Furthermore, consistent with our observations, studies have shown that C1GALT1 is overexpressed in lung adenocarcinoma tissues, with elevated expression levels strongly linked to poor prognosis in these patients." (PMID 40548474, 2025). "While a negative correlation was predominantly observed in gastrointestinal cancers, suggesting a possible immunosuppressive role for C1GalT1, other cancers like lung adenocarcinoma and breast invasive carcinoma showed positive correlations." (PMID 40548474, 2025). "The present study aimed to elucidate the clinical significance of C1GALT1 aberrant expression and its impact on radiosensitivity in lung adenocarcinoma (LUAD)." (PMID 38662050, 2024). "In this study, through bioinformatic analysis and clinical validation, we first discovered that C1GALT1 expression was upregulated in lung adenocarcinoma (LUAD) tissues and was closely related to poor prognosis in patients with LUAD." (PMID 34307388, 2021).